LINC01088 (long independently transcribed non-coding RNA 1088)
Gene: Long non-coding RNA gene on chromosome 4 (78,938,871 to 79,309,673, forward strand). Ensembl gene ENSG00000249307.
Diseases named in the same sentence as LINC01088 in open-access papers:
LINC01088 is named in the same sentence as 11 diseases in open-access papers, as found by Europe PMC text mining. Sharing a sentence is not in itself a finding about the gene and the disease. The quoted sentences say what the papers report.
colorectal cancer (4 papers, 2023 to 2025). A primary or metastatic malignant neoplasm that affects the colon or rectum. "LINC01088 overexpression has recently been shown to facilitate colorectal cancer progression by regulating key miRNAs resulting in immune escape." (PMID 39123378, 2024). "LINC01088 directly targets miR‐548b‐5p and miR‐548c‐5p, promoting the expression of G3BP1 and PD‐L1, thereby driving colorectal cancer progression and immune evasion." (PMID 40000422, 2025). "LINC01088 directly targets miR-548b-5p and miR-548c-5p, as well as enhances the expression of G3BP1 and PD-L1, consequently boosting the development of colorectal cancer and immune evasion." (PMID 36983670, 2023).
glioma (4 papers, 2022 to 2024). A benign or malignant brain and spinal cord tumor that arises from glial cells (astrocytes, oligodendrocytes, ependymal cells). "LINC01088 physically binds SNRPA and SNRPA is implicated in the tumor-promoting properties of LINC01088 in glioma." (PMID 35392763, 2022). "In sum, these observations disclosed that SNRPA is an essential downstream factor for LINC01088 exerting cancer-promoting actions in glioma." (PMID 35392763, 2022). "Overall, this study verified the function and mechanism of the LINC01088/SNRPA regulatory axis in glioma." (PMID 35392763, 2022). "In the current study, we found that attenuation of LINC01088 expression impaired glioma cell proliferation, clonogenic activity, and the invasive phenotype in vitro." (PMID 35392763, 2022). "Consistently, attenuation of LINC01088 expression exhibited tumor-inhibition effect in glioma cells growth in vivo." (PMID 35392763, 2022). "Here, we uncovered a differentially expressed long intergenic non-coding RNA 1088 (LINC01088) in glioma and elucidated the molecular mechanism by which LINC01088 affected the malignant phenotypes of glioma cells." (PMID 35392763, 2022). "In this study, with the assistance of RNA-seq, we identified that LINC01088 is highly expressed in glioma." (PMID 35392763, 2022). "In the current study, we identified that the LINC01088 level is significantly elevated in glioma when compared with that in normal." (PMID 35392763, 2022). "Functionally, LINC01088 silencing degraded cell proliferation, invasion in glioma, while LINC01088 overexpression elicited opposite results." (PMID 35392763, 2022). "In addition, among central nervous system tumors, LINC01088 exerts pro-oncogenic activities in glioma via binding to SNRPA and regulating SNRPA mRNA transcription." (PMID 36983670, 2023). "Moreover, we tested the endogenous expression level of LINC01088 in glioma cell lines, and the level of LINC01088 was remarkedly raised in glioma cells when compared with HMC3." (PMID 35392763, 2022). "Furthermore, LINC01088 expression was positively correlated with SNRPA expression in serum specimens from patients with glioma." (PMID 35392763, 2022). "Importantly, qRT-PCR also displayed that in high-grade glioma, the relative levels of LINC01088 and SNRPA were higher than in low-grade glioma (p < 0.01)." (PMID 35392763, 2022). "This work indicates that LINC01088 acts as a tumor promoter in glioma and might be an emerging target against glioma." (PMID 35392763, 2022). "Our results for the first time manifested the biological meaning of LINC01088 and indicated that LINC01088 might serve as a candidate target for glioma." (PMID 35392763, 2022). "In sum, we uncovered an upregulated lncRNA, LINC01088 in glioma." (PMID 35392763, 2022). "All these data indicated that LINC01088 expression is elevated in glioma." (PMID 35392763, 2022). "We noticed that the LINC01088 level in glioma tissue was higher than in normal tissue." (PMID 35392763, 2022). "Since SNRPA expression is regulated by LINC01088 in a transcriptional manner, we presumed SNRPA might be a critical element for LINC01088 in glioma progression." (PMID 35392763, 2022). "Our study also shown the LINC01088 level is positively correlated with SNRPA level in glioma." (PMID 35392763, 2022). "However, the specific expression and functional implication of LINC01088 in glioma remain unreported." (PMID 35392763, 2022). "We demonstrated that LINC01088 was upregulated in glioma tissues and cell lines." (PMID 35392763, 2022). "However, the specific role of LINC01088 in glioma remains poorly elucidated." (PMID 35392763, 2022). "Also, LINC01088 knockdown inhibited the tumorigenic property of glioma cells in vivo." (PMID 35392763, 2022). "Analogous to LINC01088 inhibition, attenuation of SNRPA expression had a suppressive effect in glioma cells clonogenic and invasive phenotype." (PMID 35392763, 2022).
glioma (continued). "Mechanistically, LINC01088 exerted the pro-oncogenic functions through binding with SNRPA and transcriptionally regulating SNRPA mRNA in glioma." (PMID 35392763, 2022). "Our findings revealed a novel mechanism by which LINC01088 exerted pro-oncogenic functions through binding with SNRPA and transcriptionally regulating SNRPA mRNA in glioma." (PMID 35392763, 2022). "Further rescue experiments confirmed that linc01088 can physically interact with Small Nuclear Ribonucleoprotein Polypeptide A (SNRPA) and regulate the expression of SNRPA at the transcriptional level, thereby inducing the growth of glioma cells." (PMID 38967893, 2024).
non-small cell lung carcinoma (4 papers, 2020 to 2025). A group of at least three distinct histological types of lung cancer, including non-small cell squamous cell carcinoma, adenocarcinoma, and large cell carcinoma. "LINC01088 suppresses p21 and promotes cell proliferation by interacting with EZH2 in non‐small cell lung cancer." (PMID 40000422, 2025). "In human non-small cell lung cancer (NSCLC), LINC01088 accelerates cell growth through scaffolding Enhancer Of Zeste 2 Polycomb Repressive Complex 2 Subunit (EZH2) and lessening p21." (PMID 35392763, 2022).
colon cancer (1 paper, 2019).
epithelial ovarian tumors (1 paper, 2018). "In this study, we discovered that the expression of long intergenic non-coding RNA 1088 (LINC01088) was clearly reduced in benign epithelial ovarian tumor tissues compared to matched normal ovarian tissues." (PMID 29440672, 2018). "Additionally, LINC01088 expression declined even more in borderline and malignant epithelial ovarian tumors." (PMID 29440672, 2018). "This implies that LINC01088 might inhibit the development of epithelial ovarian tumors through its interaction with miR-24-1-5p and the downstream effector protein PAK4." (PMID 29440672, 2018).
ovarian carcinoma (1 paper, 2018). A malignant neoplasm originating from the surface ovarian epithelium. "Further exploration indicated that miR-24-1-5p was a target of LINC01088, which provided experimental support for the role of LINC01088 in effective suppression of the occurrence of epithelial ovarian cancers." (PMID 29440672, 2018). "Furthermore, we found that LINC01088 inhibited the growth of ovarian cancer xenografts in nude mice." (PMID 29440672, 2018).
prostate carcinoma (1 paper, 2023). A carcinoma that arises from epithelial cells of the prostate gland. "Moreover, based on our observations, LINC01088 is preferentially localized in the cytoplasmic region of these cells, implying that its effect on prostate cancer pathophysiology may be mediated by a competing endogenous RNA (ceRNA) mechanism." (PMID 37501932, 2023). "However, the molecular mechanism by which LINC01088, which is considered an oncogene in most cancers, operates in prostate cancer has not yet been elucidated." (PMID 37501932, 2023).
prostate tumor (1 paper, 2023). "LINC01088 or CDC6 was upregulated in prostate tumor tissues or cells, whereas miR-22 was downregulated, miR-22 directly targets both LINC01088 and CDC6." (PMID 37501932, 2023).
tumor (4 papers, 2018 to 2025). "These previous studies indicate that LINC01088 plays a critical role in tumour initiation and progression." (PMID 40000422, 2025). "After cells were inoculated into nude mice, we observed that knockdown of LINC01088 substantially prohibited tumor growth in contrast to the sh-NC group." (PMID 35392763, 2022). "The tumor growth assay showed that LINC01088 significantly inhibited tumor growth, implying that LINC01088 was a tumor suppressor gene, although its mechanism remained unclear." (PMID 29440672, 2018). "Although LINC01088 has been found to promote or suppress tumours in other cancers, its regulatory mechanism in GBM remains unclear, and its association with ferroptosis has not been investigated." (PMID 40000422, 2025). "Notably, knockdown of LINC01088 led to reduced tumour growth and improved survival in the LINC01088‐SH group compared to those in the LINC01088‐NC group." (PMID 40000422, 2025). "Conversely, LINC01088‐OE promoted tumour growth and reduced survival." (PMID 40000422, 2025). "Moreover, we performed in vivo experiment with cells stably overexpressing miR-24-1-5p + LINC01088, the result showed that LINC01088 inhibited tumor growth facilitated by miR-24-1-5p." (PMID 29440672, 2018). "We conclude that LINC01088 might function as a tumor suppressor, inhibiting the tumorigenesis of ovarian epithelial cells through LINC01088/ miR-24-1-5p/ PAK4 axis." (PMID 29440672, 2018). "For instance, LINC01088 modulates the miR‐95/LATS2 pathway through a ceRNA mechanism, inhibiting tumour cell growth." (PMID 40000422, 2025). "Initially, we investigated the oncogenic function of LINC01088 and CDC6 and the tumor-suppressing role of miR-22 in PCa." (PMID 37501932, 2023). "Further studies substantiated that LINC01088 interacted with SNRPA and SNRPA mainly mediated the tumor-promoting effect of LINC01088." (PMID 35392763, 2022). "Compared with the normal group, the expression levels of the most significant four lincRNAs (LINC01088, LINC01018, LINC01436 and LINC00243) were remarkably down-regulated in the tumor group, and the down-regulation of LINC01088 was the most marked." (PMID 29440672, 2018).
cancer (3 papers, 2022 to 2025). A tumor composed of atypical neoplastic, often pleomorphic cells that invade other tissues. "LINC01088 is significantly overexpressed in GBM plays a regulatory role in various cancers." (PMID 40000422, 2025). "LINC01088 is an influential regulatory factor in various cancers." (PMID 37501932, 2023). "Furthermore, LINC01088 plays a role as a ceRNA, a miRNA sponging factor, in cancers." (PMID 37501932, 2023). "CDC6 promoted cancer cell growth and enhanced PI3K/AKT signaling and reversed the effect of si-LINC01088 on PCa cells." (PMID 37501932, 2023).
LINC01088 also shares sentences with these, for which no sentence is quoted: glioblastoma (2 papers).